IL6 (interleukin 6)
Diseases named in the same sentence as IL6 in open-access papers (continued):
Sharing a sentence is not in itself a finding about the gene and the disease.
Neonatal sepsis (continued). "Results of ANOVA model revealed that the superiority index of IL-6, IL-8, IL-10, and IL-27 were 1.20 (0.14, 5.00), 5.14 (0.33, 7.00), 0.75 (0.14, 5.00), and 1.31 (0.14, 5.00) in the detection of early-onset neonatal sepsis." (PMID 38027268, 2023). "It has been reported that the increase in serum IL-6 is an early marker for the diagnosis of neonatal sepsis." (PMID 38287976, 2023). "Interleukin 6 (IL-6), associated with C-reactive protein (CRP), plays an essential diagnostic role in neonatal sepsis in premature newborns and is associated as a prognostic marker of late neonatal sepsis." (PMID 36355884, 2022). "The role of IL-6 in neonatal sepsis or intestinal necrosis has additionally been well established, presenting itself as a promising new biomarker." (PMID 34989914, 2022). "In this study, we evaluated the diagnostic and prognostic accuracy of transcriptional (CX3CR1, CD74) and proteic (IL6, IL10, IP-10, PCT) biomarkers and their association with clinics and maternal risk factors for neonatal sepsis." (PMID 36509812, 2022). "Laboratory results useful for detecting neonatal sepsis included the concentrations of IL-6 and CRP." (PMID 36233706, 2022). "Accuracy of transcriptional (CD74, CX3CR1), proteic (PCT, IL-6, IL-10, IP-10) biomarkers and clinical characteristics to diagnose and prognose neonatal sepsis were measured." (PMID 36509812, 2022). "Laboratory results useful for the early detection of neonatal sepsis included interleukin-6 (IL-6) and CRP concentrations." (PMID 36233706, 2022). "The analysis of IL-6 concentrations showed a strong predictive value for neonatal sepsis (both EOS and LOS)." (PMID 36233706, 2022). "Similar to other works, we found the IL-6 concentration to be a reliable and early-reacting parameter for diagnosing neonatal sepsis." (PMID 36233706, 2022). "IL-6 has a significant role in the early host response to infection, and its blood level changes precede that of CRP, which makes IL-6 an excellent parameter for the monitoring of neonatal sepsis." (PMID 34708133, 2021). "Combining CRP with IL-6 was more useful for the early detection of neonatal sepsis compared to each marker alone." (PMID 34708133, 2021). "Their estimated sensitivity and specificity of serum IL-6 for the detection of neonatal sepsis with PROM were 87% and 88%, respectively, which was very close to our findings." (PMID 34708133, 2021). "A previous cutoff value of 24.65 pg/ml for serum IL-6 was reported to detect neonatal sepsis with 72% sensitivity, 84% specificity, 95% PPV, and 42% NPV." (PMID 34708133, 2021). "This study was done to investigate the role of CRP, PCT, and IL-6 in promoting the early diagnosis of neonatal sepsis in an attempt to decrease morbidity and mortality." (PMID 33061986, 2020). "Both PCT and IL-6 have been suggested to be biomarkers for severe fetal infection such as neonatal sepsis." (PMID 33211747, 2020). "In the previous studies, the optimal cut-off values of IL-6 and CRP are defined inconsistently, and their diagnostic performance for identification of neonatal sepsis varies." (PMID 33233806, 2020). "Multicenter prospective studies are required to clarify the utility of LRG in comparison with CRP, PCT, and IL-6 in detecting fetal infection as well as neonatal sepsis." (PMID 33211747, 2020). "IL-6 and G-CSF have predictive value in neonatal sepsis and IL-6 remains high in newborns with poor outcome following hypoxic-ischemic encephalopathy." (PMID 32373108, 2020). "IL-6 is a critical biomarker of neonatal sepsis, a bacterial infection that can manifest in the first week of a neonate’s life, and which is by far the most common cause of childhood mortality and morbidity." (PMID 30764575, 2019). "Visfatin concentrations correlated closely with markers of inflammation including C-reactive protein, procalcitonin, interleukin-6 (IL-6), and other cytokines, confirming observations obtained in neonatal sepsis." (PMID 30224938, 2018).
Neonatal sepsis (continued). "The pooled sensitivity of IL-6 for the diagnosis of neonatal sepsis with PROM was 0.87, the pooled specificity was 0.88, the missed diagnosis rate was 0.13, and the misdiagnosis rate was 0.12, which showed that the diagnostic efficiency was high." (PMID 30461611, 2018). "The NLR of IL-6 in early/late-onset neonatal sepsis was lower than in early-onset neonatal sepsis (0.08 vs 0.22)." (PMID 30461611, 2018). "In recent years, IL-6 has been investigated for its validity in the early diagnosis of neonatal sepsis with PROM." (PMID 30461611, 2018). "Among IL-6, IL-8, and IL-10, both IL-6 and IL-8 were found to predict neonatal sepsis at cutoffs of 10.85 pg/mL (sensitivity: 92.5%; specificity: 97.6%) and 60.05 pg/mL (sensitivity: 93.7%; specificity: 65%), respectively." (PMID 28487810, 2017). "Three cytokines, IL-6, TNF-α, and IL-1β, were investigated and strongly implicated as diagnostic tools in neonatal sepsis." (PMID 28487810, 2017). "Recent studies have also established highly sensitive and specific IL-6 cutoffs for diagnosing neonatal sepsis." (PMID 28487810, 2017). "IL-6 predicted mortality due to neonatal sepsis, with a higher cutoff of 78.2 pg/mL (sensitivity: 85%; specificity: 76%)." (PMID 28487810, 2017). "In the present study, serum levels of the proinflammatory cytokines TNF-α, IL1-β, and IL-6 and the anti-inflammatory cytokines IL-4 and IL-10 were evaluated for 25 subjects with neonatal sepsis." (PMID 28367457, 2017). "Proinflammatory IL-6 and TNF-α are the major cytokines associated with NEC pathogenesis and neonatal sepsis." (PMID 27551722, 2016). "IL-1, IL-6, IL-8, and TNFα are the cytokines which have been more widely investigated as biomarkers for neonatal sepsis." (PMID 25685774, 2015). "The diagnostic value of IL-6, TNF-α, and IL-1β is limited by the time of blood sample collection, which should be as early as possible if neonatal sepsis is suspected, since these cytokines have very short half-life." (PMID 25614712, 2014). "Among the cytokines, most studies have confirmed the utility of interleukin-6 as an early marker of neonatal sepsis." (PMID 25033045, 2014). "IL-6 is an early marker in the diagnosis of neonatal sepsis, increasing several hours before the increase in C-reactive protein." (PMID 25614712, 2014). "Umbilical cord IL-6 was the only independent predictor of early-onset neonatal sepsis (odds ratio 13.6, p = 0.004)." (PMID 23894452, 2013). "After adjustment by gestational age at delivery, prenatal administration of corticosteroids and antibiotics, the logistic regression indicated that the only independent predictor of early-onset neonatal sepsis was umbilical cord blood IL-6." (PMID 23894452, 2013). "Relationship between umbilical cord blood IL-6 and funisitis and early-onset neonatal sepsis analyzed by binary logistic regression." (PMID 23894452, 2013). "Recently, data from these five studies were consolidated into a meta-analysis45that showed that the SNP IL-6-174 had a modest carrier C effect in relation to neonatal sepsis (RR 0.9; 95% CI 0.62-1.31)." (PMID 24310803, 2013). "Evaluation of umbilical cord IL-6 and funisitis as predictors of early-onset neonatal sepsis in PPROM." (PMID 23894452, 2013). "Main finding of this study is that umbilical cord blood IL-6 is the only independent predictor of early-onset neonatal sepsis." (PMID 23894452, 2013). "Kocabas (2007) concluded that PCT and tumor necrosis factor-α are best markers in the diagnosis of neonatal sepsis in comparison with IL-6, IL-8 and CRP." (PMID 23493845, 2012). "Neonatal sepsis is a pathological condition associated with elevated levels of pro-inflammatory cytokines, including IL-1β, TNF-α, and IL-6." (PMID 22114550, 2011). "Elevation of IL-6 has been observed in human adult and neonatal sepsis, and shown to correlate with increased mortality." (PMID 20593014, 2010). "Interleukin-6 (IL-6) is emerging as a candidate for a possible early marker of neonatal sepsis." (PMID 40892314, 2025).
Neonatal sepsis (continued). "For example, novel nanotechnology-based biosensors have achieved rapid detection of pathogens in serum samples within seconds, and POCT systems for biomarkers like C-reactive protein, procalcitonin, and interleukin-6 are increasingly used in neonatal sepsis management." (PMID 40830514, 2025). "However, in contrast to TNF-α and IL-6, IL-1β serum levels are extremely low (<50 pg/mL) during neonatal sepsis." (PMID 38562936, 2024). "Interleukin-6 (IL-6) is a promising marker for neonatal sepsis." (PMID 38671704, 2024). "Serum interleukin-6 has high accuracy for the detection of neonatal sepsis." (PMID 36216867, 2023). "Interleukin-6 (IL-6) is another potentially useful marker that has been studied in neonatal sepsis." (PMID 36830264, 2023). "Findings of this network meta-analysis suggest that interleukins including IL-6, IL-8, IL-10, and IL-27 may have favorable performance in the detection of neonatal sepsis." (PMID 38027268, 2023). "IL-6 has been linked to infection, AKI (also in newborns), and possibly neonatal sepsis." (PMID 34846061, 2022). "The cytokine IL-6 is a particularly early marker of neonatal sepsis." (PMID 35345614, 2022). "Early studies, but also more recent ones on diagnostic accuracy of IL-6, e.g., were conducted in a study population of neonatal sepsis cases without further differentiation." (PMID 35345614, 2022). "Excess IL-6 levels may lead to neonatal sepsis, periventricular leukomalacia and necrotizing enterocolitis." (PMID 34046191, 2021). "A published study focusing on neonatal sepsis in 2018 suggested that the expression of IL-6 was significantly upregulated in PBMCs, which may be associated with the downregulation of miR-26a expression." (PMID 34504813, 2021). "IL-10, together with IL-6 and IL-8, are initial markers with high specificity for neonatal sepsis." (PMID 33659006, 2021). "IL-6 level increases in early disease stages of bacterial infections, and this may be useful for the early identification of neonatal sepsis." (PMID 33233806, 2020). "Noteworthy, IL-6 and IL-10 have also been recommended as indicators of neonatal sepsis and increased levels of IL-6 and TNFα in vaginal secretions of women with preterm premature rupture of membranes were good predictors of fetal inflammatory response syndrome." (PMID 33396944, 2020). "The diagnostic performance of these combinations is higher than the use of IL-6 or CRP alone as these combinations showed markedly increased sensitivity and NPV with a slightly decreased specificity and PPV compared with the use of IL-6 or CRP alone for the diagnosis of neonatal sepsis." (PMID 33233806, 2020). "Besides, the PLR of IL-6 in early/late-onset neonatal sepsis was higher than in early onset neonatal sepsis (31.84 vs 5.12)." (PMID 30461611, 2018). "Excluding the study that showed high concerns in reference standard, the pooled sensitivity, specificity, and AUC of IL-6 for neonatal sepsis with PROM were 0.85 (95% CI: 0.78–0.90), 0.87 (95% CI: 0.84–0.90), and 0.9410, respectively, which showed high stability." (PMID 30461611, 2018). "The overall accuracy of IL-6 for the diagnosis of neonatal sepsis with PROM was favorable." (PMID 30461611, 2018). "This ratio suggests a potential role for IL-6 for neonatal sepsis with PROM." (PMID 30461611, 2018). "As evidenced by these studies, IL-6, IL-8, and IL-10 may be the most promising cytokine biomarkers to diagnose neonatal sepsis once more narrow ranges in cutoffs across studies are established." (PMID 28487810, 2017). "Therefore, other bio-fluid, such as urine, was reported to detect neonatal sepsis through an elevated IL-6." (PMID 28796061, 2017). "Humoral and cellular systems are activated in the first hours of neonatal sepsis, various molecules such as Interleukin-6 (IL-6), Procalcitonin (PCT), C-reactive protein (CRP), and IL-8 released in the serum which mediated the host response to bacterial infection." (PMID 25996378, 2015).
Neonatal sepsis (continued). "Moreover, IL-6 has been correlated with maternal chorioamnionitis and used in the initial diagnosis of early neonatal sepsis when detected at high levels in umbilical cord blood." (PMID 25614712, 2014). "The most powerful indicator for the prognosis of neonatal sepsis was IL-6 both at 24 and 48 hours." (PMID 23869218, 2013). "Umbilical cord IL-6 was the only predictor of early-onset neonatal sepsis in PPROM." (PMID 23894452, 2013). "Finally, logistic regression was performed to evaluate the independence of umbilical cord blood IL-6 and funisitis to predict early-onset neonatal sepsis." (PMID 23894452, 2013). "Some cytokines (IL-6, IL-8, and tumor necrosis factor) and cell adhesion molecules (preseason, soluble triggering receptor, and cluster differentiation molecule-64) may have potential applications in treating neonatal sepsis." (PMID 40150583, 2025). "However, as the CRP elevation is known to be delayed for a considerable time, the sensitivity of the initial CRP concentration will probably never be high enough to suffice as a sole parameter for detecting neonatal sepsis and needs to be combined with other parameters, such as IL-6." (PMID 36233706, 2022). "Moreover, both TNF-α and IL-6 levels of septic serum samples were highly increased, and could be used in diagnosis and therapeutic management of neonatal sepsis." (PMID 33382782, 2020). "The true accuracy of IL-6 tests for neonatal sepsis and PROM may be lower than our report." (PMID 30461611, 2018). "The diagnostic accuracy of IL-6 is not influenced by types of neonatal sepsis." (PMID 30461611, 2018). "Therefore, IL-6 may represent a precocious marker of neonatal sepsis but in most circumstances clinicians may arrive too late for the detection of increased levels." (PMID 25685774, 2015). "The aim of this study was to determine the potential of early inflammatory markers to diagnose late-onset neonatal sepsis—procalcitonin (PCT), interleukin 6 (IL-6), interleukin 8 (IL-8) and endocan (ESM-1)." (PMID 37755410, 2023). "IL-6 and IL-12/23p40 are other cytokines that go together with IL-8, IL-10, and TNF-α as biomarkers of prenatal and postnatal inflammation and neonatal sepsis." (PMID 36768650, 2023). "The high sensitivity and negative predictive value of IL-6 make it a suitable candidate for diagnosing neonatal sepsis in combination with the high specific CRP, but reliable cut-off values for serum IL-6 in term and preterm infants are missing." (PMID 36216867, 2023). "Interleukin-6 (IL-6) is part of the fetal inflammatory response syndrome (FIRS) and therefore an interesting early marker for neonatal sepsis." (PMID 35402358, 2022). "In neonatal sepsis, a positive correlation was observed between sTREM-1 and TNF-α and other pro-inflammatory cytokines such as IL-6 and IL-8." (PMID 35402286, 2022). "Inflammatory protein markers such as those regulated by IL-6, like C-reactive protein (CRP), are important clinical analytes for early onset neonatal sepsis." (PMID 34597920, 2021). "PCT has satisfactory characteristics as a good marker than IL-6 and CRP for the diagnosis of neonatal sepsis." (PMID 33061986, 2020). "We recommend the combination of IL-6 (≥313.5 pg/mL) and CRP 1 (≥2.15 mg/L) or CRP 2 (≥8.01 mg/L) for early and accurate diagnosis of neonatal sepsis." (PMID 33233806, 2020). "Interleukin-6 (IL-6) and C-reactive protein (CRP) are the two most commonly used markers for the diagnosis of neonatal sepsis." (PMID 33233806, 2020). "This is in agreement with Al-Zahrani and coworkers, who suggested that PCT is more accurate than IL-6 and CRP in neonatal sepsis diagnosis." (PMID 33061986, 2020). "Several biochemical and immunological markers increase in the plasma during neonatal sepsis, such as increased CRP, IL-6, TNF-α, procalcitonin, and E-selectin." (PMID 33233806, 2020).
Neonatal sepsis (continued). "In this study, we attempt to define the optimal cut-off values of serum IL-6 and CRP using ROC curves, and evaluate their performance for early diagnosis of neonatal sepsis." (PMID 33233806, 2020). "This study aims to investigate the optimal cut-off levels and performance of IL-6 and CRP for the diagnosis of neonatal sepsis." (PMID 33233806, 2020). "We recommend the combination of IL-6 (≥313.5 pg/mL) and CRP1 (≥2.15 mg/L) or IL-6 (≥313.5 pg/mL) and CRP2 (≥8.01 mg/L) for early and accurate diagnosis of neonatal sepsis." (PMID 33233806, 2020). "The results indicate that the inflammatory mediators IL-1β, IL-6, IL-8, and TNF-α can be used to diagnose and assess the therapeutic efficacy of neonatal sepsis." (PMID 31671729, 2019). "For instance, tumor necrosis factor alpha (TNF-α), interleukin-1-beta (IL-1β), interleukin-6 (IL-6), and CXCL8 (interleukin-8) levels become rapidly and substantially increased during neonatal sepsis." (PMID 28367457, 2017). "To evaluate the association of CRP and inflammatory cytokines in the context of neonatal sepsis, we conducted correlation analysis between CRP and the cytokines TNF-α, IL-6, and IL-10." (PMID 28367457, 2017). "In final The combination of IL-6, hs-CRP, and PCT seems to be predictive in diagnosis of early onset neonatal sepsis." (PMID 22708043, 2012). "Among the numerous biomarkers in the field of neonatal sepsis diagnosis, this review identified 8 predominant markers, as determined by number of publications: CRP, PCT, IL-6, IL-8, IFN-γ, TNF-α, CD64 and sICAM." (PMID 23198119, 2011). "Serum levels of IL-1β, IL-6, IL-8, and TNF-αare mediators of inflammation and can be used at the diagnosis and at theevaluation of the therapeutic efficiency in neonatal sepsis." (PMID 18274637, 2007). "NET-associated biomarkers do not improve diagnostic accuracy for neonatal sepsis beyond CRP and IL-6." (PMID 42196477, 2026). "First, the cytokines IL-6, TNF, and IL-10 have been found in many studies to be significantly elevated in human infants experiencing LOS, as well as other mouse models of neonatal sepsis." (PMID 40557325, 2025). "IL-6 is not commonly available (it is neither cost-effective nor cost-saving), and procalcitonin is known to exhibit physiological elevations in the early postnatal period (it may sometimes lead to confusion regarding the prediction of early-onset neonatal sepsis), limiting its diagnostic utility." (PMID 40564685, 2025). "IL-6 has been shown to be superior to CRP in the diagnosis of late-onset neonatal sepsis due to coagulase-negative staphylococci." (PMID 35345614, 2022). "The combination of IL-6 with CRP 1, CRP 2, CRP3, CRP 4, or CRP 5 showed superior sensitivity with a slight decrease in specificity than the use of IL-6 or CRP alone for the diagnosis of neonatal sepsis." (PMID 33233806, 2020). "IL-6 and CRP are being used most commonly for the diagnosis of neonatal sepsis." (PMID 33233806, 2020). "For example, IL-6, IL-8 and C-reactive proteins are often targeted as a panel of biomarkers for reliable and sensitive diagnoses of neonatal sepsis, rather than merely IL-6." (PMID 30764575, 2019). "Interleukin-6 (IL-6) has been investigated for early diagnosis of neonatal sepsis, but not for diagnosis of neonatal sepsis with PROM." (PMID 30461611, 2018). "Because IL-6 is the main cytokine involved in the development of the fetal inflammatory response syndrome, it has been described as an early marker of BPD and neonatal sepsis." (PMID 25799377, 2015). "Cytokines (IL-6, IL-8 and TNF-α), sCD163, and C-reactive protein were serially measured in an attempt to identify a set of tests which can reliably confirm or refute the diagnosis of neonatal sepsis at an early stage." (PMID 23869218, 2013).